PLA2G2E (phospholipase A2 group IIE)
Description:
Secretory calcium-dependent phospholipase A2 that primarily targets extracellular phospholipids. Hydrolyzes the ester bond of the fatty acyl group attached at sn-2 position of phospholipids (phospholipase A2 activity), releasing various unsaturated fatty acids including oleoate, linoleoate, arachidonate, docosahexaenoate and lysophosphatidylethanolamines in preference to lysophosphatidylcholines. In response to high-fat diet, hydrolyzes minor lipoprotein phospholipids including phosphatidylserines, phosphatidylinositols and phosphatidylglycerols, altering lipoprotein composition and fat storage in adipose tissue and liver (By similarity). May act in an autocrine and paracrine manner. Contributes to lipid remodeling of cellular membranes and generation of lipid mediators involved in pathogen clearance. Cleaves sn-2 fatty acyl chains of phosphatidylglycerols and phosphatidylethanolamines, which are major components of membrane phospholipids in bacteria. Acts as a hair follicle phospholipase A2. Selectively releases lysophosphatidylethanolamines (LPE) and various unsaturated fatty acids in skin to regulate hair follicle homeostasis (By similarity). May regulate the inflammatory response by releasing arachidonate, a precursor of prostaglandins and leukotrienes. Upon allergen exposure, may participate in allergic inflammatory response by enhancing leukotriene C4 synthesis and degranulation in mast cells (By similarity).
Synonyms: GIIE sPLA2; sPLA2-IIE
Tractability: Small molecule: a structure with a bound ligand is known; a high-quality ligand is known; it belongs to a druggable protein family. Antibody: UniProt places it where antibodies can reach, with high confidence; its Gene Ontology location is reachable by antibodies, with high confidence; UniProt predicts a signal peptide or a membrane-spanning region. PROTAC: a small molecule that binds it is known.
Target class: Enzyme; Hydrolase
Gene: Protein-coding gene on chromosome 1 (19,920,009 to 19,923,617, reverse strand). Ensembl gene ENSG00000188784.
Subcellular location: Secreted; Cytoplasm
Pathways (Reactome):
Metabolism: Acyl chain remodelling of PC; Acyl chain remodelling of PE; Acyl chain remodelling of PG; Acyl chain remodelling of PI; Acyl chain remodelling of PS; Synthesis of PA
Gene Ontology:
Molecular function: calcium ion binding; phospholipase A2 activity; protein binding; phospholipid binding
Biological process: inflammatory response; phosphatidylcholine metabolic process; phosphatidylglycerol metabolic process; phospholipid metabolic process; arachidonate secretion; lipid catabolic process
Cellular component: cytoplasm; extracellular region
Genetic constraint (gnomAD): Loss-of-function variants: 14 observed, 17.01 expected, observed/expected ratio (o/e) 0.82, 90% interval 0.54 to 1.29. The upper end of that interval is the gene's LOEUF score, 1.29, which puts it in group 5 of 6, group 1 being the genes least tolerant of losing a copy. Missense variants: 174 observed, 196.6 expected, observed/expected ratio (o/e) 0.89, 90% interval 0.78 to 1. Synonymous variants: 72 observed, 79.33 expected, observed/expected ratio (o/e) 0.91, 90% interval 0.75 to 1.1.
Homologues: Orthologues: chimpanzee PLA2G2E (98% identical), macaque PLA2G2E (96% identical), pig PLA2G2E (87% identical), rabbit PLA2G2E (86% identical), mouse Pla2g2e (85% identical), rat Pla2g2e (83% identical), dog PLA2G2E (80% identical), guinea pig PLA2G2E (77% identical), Caenorhabditis elegans C03H5.4 (29% identical), Caenorhabditis elegans C07E3.9 (28% identical). Paralogues in human: PLA2G2A (51% identical), PLA2G5 (42% identical), PLA2G2F (40% identical), PLA2G2D (38% identical), PLA2G10 (37% identical), PLA2G1B (36% identical), PLA2G2C (30% identical), OC90 (29% identical).
Diseases named in the same sentence as PLA2G2E in open-access papers:
PLA2G2E is named in the same sentence as 7 diseases in open-access papers, as found by Europe PMC text mining. Sharing a sentence is not in itself a finding about the gene and the disease. The quoted sentences say what the papers report.
Obesity (2 papers, 2017 to 2021). Accumulation of substantial excess body fat. "And it was reported that members of the phospholipase A2 (PLA2) family of enzymes, such as PLA2G1B, PLA2G5, and PLA2G2E, can serve a distinct role in generating active lipid metabolites, which can promote inflammatory metabolic diseases including obesity." (PMID 29132311, 2017).
colorectal cancer (1 paper, 2008). A primary or metastatic malignant neoplasm that affects the colon or rectum. "Interestingly, the PLA2G2A, PLA2G2C, PLA2G2D, PLA2G2E, PLA2G2F and PLA2G5 genes reside within the same region of human chromosome 1 at p35–36.1, a region frequently altered in colorectal cancer." (PMID 18212756, 2008).
Stroke (1 paper, 2026). Sudden impairment of blood flow to a part of the brain due to occlusion or rupture of an artery to the brain. "Furthermore, recent research suggests that lipid metabolism mediated by phospholipase PLA2G2E in peri-infarct neurons might trigger endogenous neuroreparative pathways, offering a new perspective on the function of lipids during the recovery phase after stroke." (PMID 41432712, 2026).
PLA2G2E also shares sentences with these, for which no sentence is quoted: asthma (1 paper); breast carcinoma (1); cancer (1); myocardial ischemia (1).